HTR5A (5-hydroxytryptamine receptor 5A)
Description:
G protein-coupled receptor for 5-hydroxytryptamine (serotonin), a biogenic hormone that functions as a neurotransmitter, a hormone and a mitogen. Also functions as a receptor for ergot alkaloid derivatives and other psychoactive substances. Ligand binding causes a conformation change that triggers signaling via guanine nucleotide-binding proteins (G proteins) and modulates the activity of downstream effectors. HTR5A is coupled to G(i)/G(o) G alpha proteins and mediates inhibitory neurotransmission: signaling inhibits adenylate cyclase activity and activates a phosphatidylinositol-calcium second messenger system that regulates the release of Ca(2+) ions from intracellular stores.
Synonyms: 5-HT5A
Tractability: Small molecule: an approved drug acts on it; a structure with a bound ligand is known; a high-quality ligand is known; it belongs to a druggable protein family. Antibody: UniProt places it where antibodies can reach, with high confidence; its Gene Ontology location is reachable by antibodies, with high confidence; UniProt predicts a signal peptide or a membrane-spanning region. PROTAC: a small molecule that binds it is known.
Target class: Monoamine receptor; Family A G protein-coupled receptor; Small molecule receptor (family A GPCR); Serotonin receptor; Membrane receptor
Chemical probes: SB 699551
Gene: Protein-coding gene on chromosome 7 (155,070,324 to 155,087,392, forward strand). Ensembl gene ENSG00000157219.
Subcellular location: Cell membrane
Pathways (Reactome):
Signal Transduction: G alpha (i) signalling events; Serotonin receptors
Gene Ontology:
Molecular function: G protein-coupled serotonin receptor activity; Gi/o-coupled serotonin receptor activity; protein binding; neurotransmitter receptor activity; G protein-coupled receptor activity
Biological process: adenylate cyclase-inhibiting serotonin receptor signaling pathway; chemical synaptic transmission; G protein-coupled receptor signaling pathway; G protein-coupled receptor signaling pathway, coupled to cyclic nucleotide second messenger; hippocampus development; response to estradiol
Cellular component: plasma membrane; dendrite; membrane; perikaryon; postsynaptic specialization membrane
Genetic constraint (gnomAD): Loss-of-function variants: 21 observed, 25.26 expected, observed/expected ratio (o/e) 0.83, 90% interval 0.59 to 1.2. The upper end of that interval is the gene's LOEUF score, 1.2, which puts it in group 5 of 6, group 1 being the genes least tolerant of losing a copy. Missense variants: 497 observed, 493.19 expected, observed/expected ratio (o/e) 1.01, 90% interval 0.94 to 1.09. Synonymous variants: 260 observed, 214.19 expected, observed/expected ratio (o/e) 1.21, 90% interval 1.1 to 1.35.
Homologues: Orthologues: chimpanzee HTR5A (99% identical), macaque HTR5A (98% identical), rabbit HTR5A (93% identical), dog HTR5A (91% identical), guinea pig HTR5A (89% identical), mouse Htr5a (88% identical), rat Htr5a (84% identical), tropical clawed frog htr5a (76% identical), zebrafish htr5ab (75% identical), zebrafish htr5aa (75% identical). Paralogues in human: HTR1B (35% identical), HTR1F (33% identical), HTR7 (33% identical), HTR1E (32% identical), HTR2A (27% identical), HTR2B (27% identical), HTR2C (27% identical), HTR6 (27% identical).
Diseases named in the same sentence as HTR5A in open-access papers:
HTR5A is named in the same sentence as 26 diseases in open-access papers, as found by Europe PMC text mining. Sharing a sentence is not in itself a finding about the gene and the disease. The quoted sentences say what the papers report.
depression (4 papers, 2016 to 2022). "Additionally, we detected 4 P-SMRs involved in Alzheimer’s disease (Psen2), Parkinson’s disease (Dnajc6) and major depression disorder (Htr2a and Htr5a)." (PMID 32992647, 2020).
schizophrenia (3 papers, 2016 to 2022). A major psychotic disorder characterized by abnormalities in the perception or expression of reality. "We aimed to examine the association of HTR1A and HTR5A with schizophrenia and executive function." (PMID 27897266, 2016). "Our results provide further supportive evidence of the effect of HTR1A and HTR5A on the etiology of schizophrenia and suggest that the selected genetic variations in HTR5A may be involved in impaired executive function." (PMID 27897266, 2016).
epilepsy (2 papers, 2017 to 2025). A brain disorder characterized by episodes of abnormally increased neuronal discharge resulting in transient episodes of sensory or motor neurological dysfunction, or psychic dysfunction. "MR analyses of epilepsy with FinnGen data, mainly using the methods of Wald radio and IVW, genetically predicted lower levels of HTR5A and HTR1D were associated with an increased risk of epilepsy and FE, respectively." (PMID 40170563, 2025).
mood disorder (2 papers, 2013 to 2022). A cognitive disorder a disturbance in which the person's mood is hypothesized to be the main underlying feature. "Genetic variants in genes related to serotonin transmission (e.g. HTR1B,HTR3A, HTR5A, etc) were associated with mood disorder." (PMID 23326387, 2013). "Although serotonin receptor 5A has been less studied relative to serotonin receptors 1–4, human studies have linked this receptor subtype to executive function and mood disorders and HTR5A knockout mice show increased exploratory activity in novel environments compared to controls." (PMID 35536842, 2022).
prostate carcinoma (2 papers, 2016 to 2017). A carcinoma that arises from epithelial cells of the prostate gland. "This is the first time HTR5A has been implicated in prostate cancer progression and development of HTR5A antagonists may prove to be a viable treatment option for men who develop neuroendocrine prostate cancer." (PMID 27015368, 2016). "The striking up-regulation of HTR5A mRNA and protein levels only in prostate cancer cells exposed to hypoxia and lacking Rb expression leads to the possibility that NE cells may develop sensitivity to serotonin in this fashion." (PMID 27015368, 2016).
agranulocytosis (1 paper, 2021). "The lead variant and its LD proxies at the INSIG1 locus are located in an intergenic region close to another gene HTR5A (5-hydroxytryptamine receptor 5A), which has been reported for sulfasalazine-induced agranulocytosis in EA populations." (PMID 34107879, 2021).
astrocytoma (1 paper, 2020). "By analyzing the genome-wide sequencing data of human glioma samples provided by TCGA, we found that the expression levels of HTR5A was decreased in glioblastoma patients compared to low-grade gliomas including oligodendroglioma, oligoastrocytoma, and astrocytoma." (PMID 32549758, 2020).
breast tumor (1 paper, 2020). "To validate the molecular target of the antagonists, we used the CRISPR-Cas9 gene editing technology to conditionally knockout HTR5A in a breast tumor cell line." (PMID 32758183, 2020).
glioblastoma (1 paper, 2020). The most malignant astrocytic tumor (WHO grade IV). "Based on the data from Cancer Genome Atlas (TCGA) database, we observed a downregulation of HTR5A in Glioblastoma patients, suggesting it may play negative role in GBM development." (PMID 32549758, 2020).
glioma (1 paper, 2020). A benign or malignant brain and spinal cord tumor that arises from glial cells (astrocytes, oligodendrocytes, ependymal cells). "Further analysis suggested that HTR5A had a lowest level in WHO grade IV glioma compared to others grade glioma." (PMID 32549758, 2020). "In this study, we found that one of 5-HT receptors, HTR5A, was downregulated in high grade GBM compared to low grade glioma." (PMID 32549758, 2020). "By processing Pearson correlation analysis to calculate the expression of HTR5A and PRKAA1 in different WHO grading gliomas, we found that the expression levels of HTR5A had a linear correlation with the PRKAA1 in glioma specimens, r=0.48, P <0.05." (PMID 32549758, 2020).
Joubert syndrome (1 paper, 2025). Joubert syndrome (JS) is characterized by congenital malformation of the brainstem and agenesis or hypoplasia of the cerebellar vermis leading to an abnormal respiratory pattern, nystagmus, hypotonia, ataxia, and delay in achieving motor milestones. "Of particular interest, they affected neuronal genes, including Ahi1 (implicated in Joubert syndrome), Tox3 (a calcium-dependent transactivator), and Htr5a (a serotonin receptor), all of which are implicated in neuronal function and psychiatric disorders (57, –59)." (PMID 40802685, 2025).
prostate tumor (1 paper, 2020). "Whereas the role of 5-HT5A in cancer is largely unknown, a recent study demonstrated that HTR5A was among the most differentially upregulated genes after hypoxia-mediated neuroendocrine differentiation of prostate tumor cells." (PMID 32758183, 2020).
cancer (3 papers, 2020 to 2024). A tumor composed of atypical neoplastic, often pleomorphic cells that invade other tissues. "Additionally, C5 and the high expression of HTR5A were tightly related, indicating that HTR5A may have a cancer-suppressing function, and HTR7’s high expression was related to C2, which indicated that HTR7 related to a high level of immune infiltration and intertumoral heterogeneity." (PMID 39766808, 2024).
nervous system diseases (2 papers, 2016 to 2022). "Analysis of the neurological disease network identified several key up-regulated targets such as HTR5A, KISS1R and GPR146." (PMID 27015368, 2016).
HTR5A also shares sentences with these, for which no sentence is quoted: Anxiety (2 papers); tumor (2); Alzheimer disease (1); bipolar disorder (1); breast carcinoma (1); glaucoma (1); oligoastrocytoma (1); oligodendroglioma (1); osteosarcoma (1); Parkinson disease (1); psychiatric disorder (1); psychosis (1).